CD47 (CD47 molecule)
Diseases named in the same sentence as CD47 in open-access papers (continued):
Sharing a sentence is not in itself a finding about the gene and the disease.
CD47 also shares sentences with these, for which no sentence is quoted: multiple myeloma (20 papers); neutropenia (10); anaplastic thyroid carcinoma (4); atypical teratoid rhabdoid tumor (4); brain cancer (4); diffuse intrinsic pontine glioma (4); Hodgkins lymphoma (4); leukopenia (4); angiosarcoma (3); immune disorders (3); marginal zone lymphoma (3); metastatic cancer (3); primitive neuroectodermal tumor (3); basal cell carcinoma (2); dyslipidemia (2); falciparum malaria (2); inflammatory bowel disease (2); Insulin resistance (2); Iron deficiency anemia (2); ischemic stroke (2); keratoacanthoma (2); mucinous neoplasm (2); Parkinson’s (2); pleomorphic liposarcoma (2); skin cancer (2); abdominal aortic aneurysm (1); acute leukemia (1); acute myocardial infarction (1); Allergy (1); Aortic dissection (1).
A further 86 diseases each share a sentence with CD47 in 1 paper.